ARID1A (AT-rich interaction domain 1A)
Diseases named in the same sentence as ARID1A in open-access papers (continued):
Sharing a sentence is not in itself a finding about the gene and the disease.
cancer (continued). "Therefore, it has been argued that ARID1A‐deficient cancers are sensitive to ATR inhibitors, which, in turn, promote apoptosis." (PMID 40170512, 2025). "In this review, we explore the more recent evidence suggesting that ARID1A loss contributes to notable cancer hallmarks such as genomic instability, cell cycle regulation, EMT and dedifferentiation, immune evasion, and evading cell death across various cancer types." (PMID 40429787, 2025). "ARID1A deficiencies are associated with increased microsatellite instability, higher mutational burden, greater immune infiltration, and improved response to immune checkpoint blockade in other cancer types." (PMID 41066027, 2025). "Therefore, targeting ARID1A deficiency using a synthetic lethality approach is a promising strategy for cancer treatment." (PMID 40369167, 2025). "Mutations in ARID1A/ARID1B/ARID2 render cancers more prone to immune checkpoint blockade therapies." (PMID 41278204, 2025). "The most common example of these interactions is provided by the combination of mutually exclusive gene paralogues, such as in cancers with ARID1A mutation that require ARID1B for survival or tumors with BRG1 deficiency, which are sensitive to SMARCA2 depletion." (PMID 41278204, 2025). "This work also identifies KLF5 as a potential target for treating ARID1A-deficient cancers." (PMID 39779698, 2025). "ARID1A is the most frequently mutated gene among BAF subunits (∼8% of all types of cancer)." (PMID 41017120, 2025). "Deregulated interferon signaling is frequent in cancers; an upregulation in ARID1A‐deficient cells may therefore either enhance or decrease these effects depending on the specific regulation on a cellular level." (PMID 40170512, 2025). "Additionally, ARID1A deficiency is associated with a reduced mismatch repair capacity, increased cancer mutability, and increased infiltration of immune cells, thus potentiating the efficacy of ICBs." (PMID 40750787, 2025). "For example, the manipulation of the Armadillo repeats (ARM) domain of the ARID1B subunit may disrupt ARID1B interaction with other subunits in the SWI/SNF complex and induce synthetic lethality in ARID1A-deficient cancers." (PMID 41278204, 2025). "ARID1A is frequently mutated in various cancers; however, the functional relationship and synthetic lethality mechanism between ARID1A and its homologue ARID1B remain unclear." (PMID 39779467, 2025). "Notably, FDA-approved c-MET inhibitors, such as crizotinib and cabozantinib, have demonstrated enhanced cytotoxicity in ARID1A-deficient cancers, facilitating the translation of these approved drugs for repurposing in ARID1A-targeted precision cancer medicine." (PMID 40369167, 2025). "It has been suggested that EZH2 inhibitors may prove effective in combatting cancer through the mechanism of synthetic lethality in tumors with ARID1A mutations." (PMID 39773749, 2025). "Notably, in some cancer types, ARID1A mutations have been associated with greater genomic stability based on DNA copy number variations." (PMID 40429787, 2025). "While this relationship has been underexplored in OCCC, mechanistic studies in other cancers have demonstrated that ARID1A deficiency impairs MMR protein expression through disruption of MLH1 transcription and compromises DNA mismatch repair through SWI/SNF complex-mediated chromatin remodeling." (PMID 40430056, 2025). "However, given the documented risk of inflammatory and autoimmune system complications, a deeper understanding of the interplay between EZH2 inhibitors and ICB in treating ARID1A mutated cancers remains crucial." (PMID 38893181, 2024). "Together these data suggest that KEAP1 could be pursued as a means to selectively kill certain types of ARID1A-deficient cancer." (PMID 39272807, 2024).
cancer (continued). "In many cancer types, mutations in ARID1A are the most common among genes associated with HR and were reported to account for 6.4% in OvCa, 3.7% in BC, 5.5% in PaC and 0% in PC of mutations found in a retrospective study of 21 cancer lineages." (PMID 38184614, 2024). "A large number of DEGs were detected between ARID1A-deficient and control cancer cells." (PMID 38229120, 2024). "ARID1A has a high loss of function mutation rate in many cancers." (PMID 38587186, 2024). "Loss of ARID1A in the process of carcinogenesis may make early cancer cells prone to genomic instability." (PMID 38365747, 2024). "However, mutations within the ARID1A DNA-binding domain, common in various cancers and malignancies, pose significant challenges, including therapeutic resistance and genomic instability." (PMID 39764114, 2024). "A previous study demonstrated that ARID1B exhibits specific vulnerability in human cancers with ARID1A mutations, and that ARID1A deficiency may make cancer cells more dependent on ARID1B." (PMID 38365747, 2024). "Despite the frequency of mutations, the impact on ARID1A’s stability and contribution to cancer progression remains unclear." (PMID 39764114, 2024). "Furthermore, low ARID1A expression in cancer patients receiving radiotherapy was associated with higher infiltration of several immune cells." (PMID 38587186, 2024). "In vitro studies have demonstrated that ARID1A deficiency could sensitize cancer cell lines to PARPi, BRD4 inhibitor and EZH2 inhibitor." (PMID 39104720, 2024). "Interestingly, the authors found that the vulnerability of ARID1A-deficient cancer cells is caused by low basal GSH levels due to a decreased expression of SLC7A11." (PMID 38203758, 2024). "Consequently, the loss of Arid1a leads to significant dysregulation in GI observed in various cancers, including OS." (PMID 39123453, 2024). "In conclusion, the mutation rate of ARID1A in all cancers is about 8%." (PMID 39697230, 2024). "Activation of the acylinositol triphosphate kinase (PI3K/AKT) signaling pathway is an essential mechanism for the progression of many cancers, and studies have shown that the role of ARID1A in tumors can be associated with activation of the PI3K signaling pathway." (PMID 39697230, 2024). "Notably, ARID1A mutations have been reported to occur also in preneoplastic lesions, indicating its role in early cancer development." (PMID 38893181, 2024). "ARID1A mutation may be associated with cancer cell sensitivity to EZH2 inhibitor therapy as well as PARP inhibitor drugs due to its role in DNA damage repair." (PMID 38543097, 2024). "Given the frequent mutation of ARID1A in various cancers including NSCLC, we speculated that some key target genes might be derepressed upon ARID1A loss and contribute to the progression and drug resistance of ARID1A-mutated NSCLC." (PMID 38229120, 2024). "ARID1A deficiency is associated with elevated PD-L1 expression in various cancers." (PMID 38166741, 2024). "Additionally, in ~13% of BCs, there is mostly a loss of heterozygosity of ARID1A, resulting in reduced protein expression and a more aggressive cancer phenotype." (PMID 37109525, 2023). "ARID1A deficiency was found to sensitize cancer cells to poly adenosine diphosphate (ADP) ribose polymerase (PARP) inhibitors and inhibitors of the DNA damage checkpoint kinase, ataxia telangiectasia and Rad3-related (ATR), providing rationale for clinical testing of PARP and ATR inhibitors." (PMID 37711591, 2023).
cancer (continued). "Moreover, neo-mutations in endometriotic epithelial cells of two cancer-driver genes, ARID1A and KRAS, would favor their diffusion." (PMID 36979957, 2023). "Moreover, PI3K/AKT/mTOR inhibitors, when combined with other therapies, have demonstrated effectiveness against ARID1A‐deficient cancers." (PMID 38041544, 2023). "Similar to the scenario of cell-type dependence on ARID1A, cancers displaying the highest ARID1B dependency score (lower than −0.5 or so) tend to have ARID1A mutations, further validating the close functional interaction between these two core subunits of the SWI/SNF complex." (PMID 36980292, 2023). "This suggests that targeting EZH2 could be a potential therapeutic strategy for ARID1A‐deficient cancers." (PMID 38041544, 2023). "Specific alteration and loss of function of the ARID1A gene are present in about 6% of cancers." (PMID 36770884, 2023). "Consequently, the loss of ARID1A sensitizes cancer cells to PARP inhibitors and inhibitors of DNA damage checkpoint kinase, both in laboratory studies and in animal models." (PMID 38041544, 2023). "The ARID1A-DUSP4-MAPK axis may be further considered for developing targeted therapies against ARID1A-mutated cancers." (PMID 38071325, 2023). "Conversely, loss of ARID1A may increase the risk of steatohepatitis and cancer progression by altering immunity in vivo or tumorigenesis via activation of angiopoietin-2 (ANGPT2) transcription in vitro and angiogenesis in vivo." (PMID 36844227, 2023). "ARID1A is a critical subunit of the SWI/SNF complex mutated in many cancer types." (PMID 38072854, 2023). "Finally, several promising synthetic lethal strategies, which exploit the specific vulnerabilities of ARID1A-deficient cancer cells, are briefly mentioned." (PMID 38275587, 2023). "Of the SWI/SNF components, mutations in ARID1A are the most common in human cancers." (PMID 38275587, 2023). "Deficiency of ARID1A, as a tumor suppressor gene, has been thought to significantly affect the transcriptional control of many genes contributing to carcinogenesis in several cancers." (PMID 38017409, 2023). "If these variants are germline, ARID1A might be a better indicator of cancer risk than PALB2 in the Mexican-mestizo populations." (PMID 37182128, 2023). "Changes in the expression of numerous genes (CDKN1A, SMAD3, MLH1 and PIK3IP1) caused by mutations in ARID1A contribute to the development of cancer and have been linked to the PI3K/AKT pathway in cell translocation, which was highly likely to become a therapeutic target for OC." (PMID 37525498, 2023). "ARID1A is one of the most commonly mutated genes in cancers." (PMID 37981695, 2023). "Moreover, the current study uncovers a potential ERK targeting strategy in cancers with ARID1A loss." (PMID 38071325, 2023). "A synthetic lethal treatment approach may be beneficial for treating cancers with ARID1A mutations because of the compromised DNA damage repair." (PMID 38071325, 2023). "Therefore, a combination treatment of inhibiting BCL2 and EZH2 is a better therapeutic strategy for ARID1A mutated cancers." (PMID 37093326, 2023). "The mutational profile of ARID1A-mutated cancer was explored in anectodal experiences." (PMID 37711591, 2023). "It is important to note that as revealed by the RNA-seq data of the TCGA HCC cohort, ARID1A mRNA is significantly upregulated in human HCC tumors as compared with the nontumorous liver samples, in contrast to the frequent downregulation of ARID1A protein in other ARID1A-deficient cancers." (PMID 36980292, 2023). "Eric: Collectively, these results support the concept that ARID1A pathogenic variants sensitize cancer cells to the BRD4i-ATRi combination and may serve as biomarkers to select patients for this efficacious treatment." (PMID 37841875, 2023). "Besides, the increase of vascular endothelial growth factor (VEGF), another essential angiogenic factor, has been found in the ARID1A-deficient breast and colon cancer cells." (PMID 38017409, 2023).
cancer (continued). "Finally, we demonstrate the efficiency of CRISPRi screens to identify nocodazole-dependent gene essentiality, as well as genes that impact growth differently as a result of a mutation to the ARID1A cancer and developmental disorder gene." (PMID 37028423, 2023). "The recent discovery of the SWI/SNF complex as an essential player in determining the therapeutic efficacy of cancer immunotherapy further highlights great promise for harnessing the cancer-specific vulnerability elicited by ARID1A deficiency to potentiate immunotherapy." (PMID 36980292, 2023). "Completed clinical trials involving cancers with ARID1A deficiency*." (PMID 36890819, 2023). "Hence, cancer cells with ARID1A mutation or deficiency depend more on the PI3K/Akt1 pathway than the cells expressing normal ARID1A." (PMID 36910637, 2023). "Defects in PIK3CA or PTEN, frequently co-occurring, may cooperate with ARID1A loss to drive cancer and downstream activation of the PI3K/AKT pathway." (PMID 37711591, 2023). "Given the high mutation load in MSI cancers, it is possible that the increased frequency of ARID1A deficiency may be due to ‘passenger’ mutations." (PMID 38275587, 2023). "Also, sequencing of deep endometriotic lesions has revealed known somatic cancer driver mutations in 26% of the samples, including mutations in ARID1A and PIK3CA." (PMID 37789421, 2023). "The aim of this article was to study ARID1A-mutated cancer patients." (PMID 37711591, 2023). "Since HDAC6 overexpression in ARID1A‐mutated cancers has been associated with several chemoresistant factors, we wondered whether inhibition of HDAC6 may be a promising therapy for those cancers." (PMID 35167193, 2022). "Once again, most of the work regarding ARID1A focuses on its function in transcription, but several studies have shown that this subunit is also important for the repair of DSBs, thus ARID1A-mutated cancers likely have a DNA repair vulnerability that can be exploited therapeutically." (PMID 36605718, 2022). "Thus, targeting this AMPK pathway leads to cell death preferentially in ARID1A-deficient cancer cells." (PMID 36123603, 2022). "ARID1A is the most frequently mutated subunit within the SWI/SNF complex in human cancers." (PMID 36605718, 2022). "Interestingly, ARID1A mutations and the depletion of ARID1A protein expression sensitized cancer cells to PI3K/AKT inhibitors." (PMID 35070505, 2022). "However, a different report suggested that other cancer types with loss of ARID1A are more sensitive to immune checkpoint blockade." (PMID 35323214, 2022). "In addition, loss of ARID1A renders cancer cells highly sensitive to combined therapy with PARP inhibitors and ionizing radiation." (PMID 36361605, 2022). "To gain further pathway and functional insight into possible genetic interactions underlying ARID1A deficiency-driven resistance to anti-EGFR therapy, we next searched for oncogenic dependencies or mutual exclusivities between ARID1A mutations and other alterations in cancer." (PMID 36117191, 2022). "Thus, efforts have been made to develop cancer therapeutics exploiting the mutational status of ARID1A in cancer patients." (PMID 36249060, 2022). "ARID1A mutations were found in over 30% of various cancer types." (PMID 36569894, 2022). "However, we confirmed the same trend in TCGA cohort, and there are other reports in a large cohort study with over 40 000 cases that ARID1A‐mutated cancers including CRCs had higher mutational burdens than cancers without ARID1A mutations." (PMID 34042312, 2022). "The SWI/SNF complex is mutated in > 20% of all human cancers, and the ARID1A (At‐rich interactive domain, also known as BAF250A) subunit is especially prone to somatic mutations in gynaecologic cancers, although its role in endometrial tumorigenesis is not fully understood." (PMID 35167193, 2022).
cancer (continued). "In this study, genes involved in the control of liver regeneration were the most recurrently mutated within cirrhotic nodules, including driver mutations in cancer-related gene ARID1A, which controls gene expression associated with emergence of injury-induced liver progenitor-like cells." (PMID 35814741, 2022). "Epigenetic driver mutations in ARID1A occur in human cancers and promote cancer development." (PMID 36362284, 2022). "It is worth noting that the ARID1A-deficient cancers are susceptible to the perturbance of homolog ARID1B, indicating that synthetic lethality may be a possible therapeutic option in these specific tumors." (PMID 35303910, 2022). "There is evidence indicating that ARID1A-mutated cancers may also be vulnerable to therapeutic intervention by targeting the PI3K/AKT pathway." (PMID 35070505, 2022). "Due to ARID1A’s involvement in DDR responses, ARID1A mutant cancers may be more susceptible to ATR blockade and PARP inhibition." (PMID 36430148, 2022). "Furthermore, ARID1A-deficient cancer cells are specifically vulnerable to EZH2 inhibitors, HDAC inhibitors and some other selective inhibitors." (PMID 36180906, 2022). "We then explored the role of ARID1A expression, which may be downregulated by ARID1A mutations, in cancer immunity and immunotherapy." (PMID 36229854, 2022). "Similarly, Tsai and colleagues found that the core DNA-binding subunit of the BAF complex ARID1A had a profound impact on DNA replication stress management, indicating the potential treatment strategy of targeting ARID1A-deficient cancers." (PMID 36361605, 2022). "In particular, ARID1A, which has biological functions as an essential molecule in DNA repair and stabilization, can be dysregulated in malignancies and is associated with cancer development." (PMID 36229854, 2022). "Recently, the role of PLK1 in ARID1A-deficient cancer cells has been reported." (PMID 36123603, 2022). "ARID1A mutations have been reported in many types of human cancers, including FL." (PMID 34791836, 2022). "In addition, loss of the SWI/SNF subunit ARID1A is further reported to be associated with increased sensitivity to PI3K/Akt inhibition in cancer." (PMID 35794096, 2022). "Cancer patients harboring mutated ARID1A, ARID1B or ARID2 benefit more from cancer immunotherapy." (PMID 35239432, 2022). "Moreover, studies also suggest that ARID1B can be a particularly interesting target in ARID1A-mutated cancers." (PMID 36605718, 2022). "ARID1A mutation was correlated with high immune infiltrates in most of the cancer types." (PMID 35003124, 2021). "Addressing the main stems of the disease is also appealing: ARID1A loss sensitizes cancer cells to poly(ADP-ribose) polymerase (PARP) inhibitors, and some agents have shown demethylating activity, providing candidate therapeutic opportunities for clinical trials." (PMID 33608032, 2021). "It was further shown that the suppressed SLC7A11 expression results in decreased cystine uptake and GSH biosynthesis in ARID1A-deficient cancer cells, which induces a vulnerability rendering ARID1A-deficient cancers susceptible for pharmacological inhibition of GSH biosynthesis." (PMID 33000412, 2021). "Only one study reported that ARID1A variants might serve as a cancer-promoting gene in CCA, while the remaining 28 included studies indicated ARID1A variants might be a suppressor in CCA development and progression." (PMID 34249744, 2021). "There are some ongoing trials that target ARID1A-associated cancers." (PMID 34680987, 2021). "ARID1A mutation in cancer was found to occur synergistically with PIK3CA." (PMID 34217266, 2021). "Tumor suppressor ARID1A is frequently mutated in multiple forms of cancers." (PMID 33000412, 2021). "Additionally, ARID1A deficiency was revealed to contribute to sensitization of cancer cells to Poly (ADP-Ribose) Polymerase (PARP) inhibitors." (PMID 34036097, 2021).